HOXA1 (homeobox A1)
Diseases named in the same sentence as HOXA1 in open-access papers (continued):
Sharing a sentence is not in itself a finding about the gene and the disease.
B-cell lymphoma (1 paper, 2023). "In addition, miR-4284 directly inhibits the translation of genes, such as B-cell lymphoma/leukemia 10, histone deacetylase, homeobox A1, and Phosphatase and TENsin homolog deleted on chromosome 10, affecting apoptosis, differentiation, and proliferation in diffuse large B-cell lymphoma." (PMID 37568704, 2023).
chronic obstructive pulmonary disease (1 paper, 2025). A chronic and progressive lung disorder characterized by the loss of elasticity of the bronchial tree and the air sacs, destruction of the air sacs wall, thickening of the bronchial wall, and mucous accumulation in the bronchial tree. "Airway basal cells from chronic obstructive pulmonary disease patients show a reduction in HOXA1 expression and generate an abnormal airway epithelium." (PMID 40214503, 2025).
Cognitive impairment (1 paper, 2024). Abnormal cognition is characterized by deficits in thinking, reasoning, or remembering. "The results suggested that reducing miR-150 levels may alleviate VD symptoms, significantly improving cognitive impairment and reducing neuron apoptosis in the brain by upregulating homeobox A1 (HOXA1) expression." (PMID 38892378, 2024).
Congenital fibrosis of the extraocular muscles type 1 (1 paper, 2017). "Congenital fibrosis of the extraocular muscles type 1 (CFEOM1) is known to be caused by mutations in KIF21A or TUBB3 or other known genes (SALL4, CHN1, HOXA1)." (PMID 29110737, 2017).
endometriosis (1 paper, 2024). The growth of functional endometrial tissue in anatomic sites outside the uterine body. "For instance, in endometriosis, all members of the HOXA gene family (except for HOXA1) were significantly down-regulated in ectopic tissues compared to normal endometrium." (PMID 38311789, 2024). "In endometriosis, all HOXA and HOXB paralogs, except for HOXA1, exhibited significant down-regulation in ectopic tissues compared to control tissues." (PMID 38311789, 2024).
fibrosarcoma (1 paper, 2020). A malignant mesenchymal fibroblastic neoplasm affecting the soft tissue and bone. "Real-time PCR analysis showed that silencing SAPCD2 decreased expression levels of multiple downstream genes of the Hippo pathway, including CTGF, CYR61, SOX9, HOXA1, RPL13A, and PPIA in fibrosarcoma cells." (PMID 33384953, 2020).
head and neck cancer (1 paper, 2024). A primary or metastatic malignant neoplasm affecting the head and neck. "Head and neck cancer with increased expression levels of HOXA1 tends to have a worse outcome." (PMID 38473236, 2024).
laryngeal carcinoma (1 paper, 2020). Carcinoma that arises from the laryngeal epithelium. "We conducted further survival analysis in three tumor locations and found that the expression of HOXA1 only has prognostic value in oropharyngeal cancer (P < 0.05), while no significant predictive value in hypopharyngeal and laryngeal cancer (p > 0.05) in TCGA-HNSC patients." (PMID 33763449, 2020).
Moebius syndrome (1 paper, 2021). Moebius syndrome is a very rare congenital cranial dysinnervation disorder characterized by complete or incomplete facial paralysis in association with bilateral palsy of the abducens nerve causing impairment of ocular abduction. "Impairment in ocular abduction, with full ocular vertical mobility, in association with CFW suggests a diagnosis of Moebius syndrome or HOXA1 syndromes." (PMID 33827624, 2021).
oropharyngeal cancer (1 paper, 2020). Carcinoma, predominantly squamous cell, arising from the epithelial cells of the oropharynx. "Our study demonstrated that HOXA1 is highly expressed in HNSCC, which may be an independent prognostic factor in TCGA-HNSC patients, especially for oropharyngeal cancer patients." (PMID 33763449, 2020).
osteosarcoma (1 paper, 2020). A usually aggressive malignant bone-forming mesenchymal neoplasm, predominantly affecting adolescents and young adults.
respiratory failure (1 paper, 2023). The significant impairment of gas exchange within the lungs resulting in hypoxia, hypercarbia, or both, to the extent that organ tissue perfusion is severely compromised. "In the previous study, we found that the Hoxa1 mutation of g.50111251 G > TC resulted in the congestion and edema of fetal lungs, and all neonatal Hoxa1−/− piglets died of respiratory failure during the suckling period." (PMID 37760250, 2023).
schizophrenia (1 paper, 2007). A major psychotic disorder characterized by abnormalities in the perception or expression of reality.
thyroid tumor (1 paper, 2023). A benign or malignant neoplasm affecting the thyroid gland. "PTGS2, HOXA1, TMEFF2, p16, and PTEN genes were hypermethylated in FNAC of thyroid tumor when compared between the tumor and healthy tissue." (PMID 36975440, 2023).
uveal melanoma (1 paper, 2022). A melanoma derived from melanocytes of the uveal tract. "We found that high HOXA1 expression was a risk factor for poor prognosis in multiple cancers, including CESC, LGG, and UVM (uveal melanoma)." (PMID 36119466, 2022).
tumor (67 papers, 2007 to 2025). "Homeobox A1 (HOXA1) gene is a potent oncogene, and the active expression of HOXA1 is enough to cause the oncogenic transformation of human breast epithelial cells and has the ability of invasive tumor." (PMID 31772931, 2019). "A high percentage of HOXA1-positive cells was significantly associated with T stage (p = 0.039), N stage (p = 0.046) and tumor cellular differentiation (p = 0.026)." (PMID 22498108, 2012). "A high number of HOXA1-positive cells was significantly associated with T stage, N stage, tumor differentiation and proliferative potential of the tumors, and was predictive of poor survival." (PMID 22498108, 2012). "Moreover, both Gene Set Variation Analysis (GSVA) and Gene Set Enrichment Analysis (GSEA) have successfully linked HOXA1 expression to tumor-associated signaling pathways and cell adhesion junction pathways." (PMID 38311789, 2024). "Besides, we ran GSEA to figure out the significant differential signaling pathways related to the expression value of HOXA1, including neuroprotein secretion and transport, the tumor-associated signaling pathway, cell adhere junction and metabolic reprogramming." (PMID 33763449, 2020). "To further confirm whether HOXA1 is associated with the immunosuppression of MDSCs, we constructed an HOXA1 expression vector and transfected it into MDSCs isolated from the spleen of tumor-bearing mice." (PMID 29662483, 2018). "In the investigation of HOXA function in tumor treatment, findings have revealed that the methylation of HOXA1 can be induced by HOTAIR, resulting in chemoresistance in SCLC via activation of the NF-κB pathway." (PMID 38311789, 2024). "HOXA1 is acknowledged as a tumor activator due to its well-established role in promoting proliferation, migration, invasion, and aerobic glycolysis." (PMID 38311789, 2024). "HOXA1 plays a pivotal role as a tumor activator in promoting the proliferation, metastasis, and invasion of GBM." (PMID 38311789, 2024). "Patients with higher levels of the methylation of cg0765905 in tumor samples presented a prolonged overall survival (OS) compared to patients with lower levels of the methylation of this HOXA1 CpG position." (PMID 38473236, 2024). "In cancer, HOXA1-4 genes can function as either oncogenes or tumor suppressors and interact with other members of the HOX family to regulate tumor proliferation, invasion, and metastasis through signaling pathways such as JAK-STAT, MEK/ERK, and Wnt/β-catenin." (PMID 38311789, 2024). "In vitro and in vivo experiments demonstrated effective miR-218 restoration, as well as downregulation of the miR-218 target Homeobox A1 (HOXA1), responsible for tumor progression." (PMID 37576994, 2023). "In order to provide clinicians with predicted prognosis of LGG patients quantitatively, we constructed the nomogram combining HOXA1, HOXA6 expression and independent clinical risk factors (tumor grade, age, primary therapy outcome and age)." (PMID 35349479, 2022). "For example, it has been showed that HOXA1 was highly expressed in breast cancer and its high expression was correlated with poor prognosis and tumor progression of BRCA." (PMID 35349479, 2022). "HOTAIRM1 has been found to enhance the expression of HOXA1 in MDSCs, and the upregulation of HOXA1 can delay tumor progression and enhance anti-tumor immune response by restraining the immunosuppressive activity of MDSCs." (PMID 34692550, 2021). "The findings implied that after knockdown of DLX6‐AS1 or overexpression of miR‐193b‐3p, HOXA1 expression in xenografted tumours was inhibited, and vice versa." (PMID 34514705, 2021). "To this end, we downloaded all genes whose mRNA expression correlated with HOXA1 mRNA expression or with tumor ER status." (PMID 34490074, 2021). "In in vivo models, Brock and colleagues confirmed the key role of HOXA1 in mammary oncogenesis by demonstrating that silencing HOXA1 with specific siRNAs decreases tumor incidence in mice." (PMID 34490074, 2021).
tumor (continued). "The high expression of HOXA1 in human BC cells can promote tumor cell proliferation, mainly through the promotion of cell survival mediated by up-regulation of Bcl-2 transcription." (PMID 34180753, 2021). "To explore the underlying mechanisms behind HOXA1, we ran GSVA and GSEA and found fourteen mutual signaling pathways, including neuroprotein secretion and transport, tumor-associated signaling pathways, cell adhere junction and metabolic reprogramming." (PMID 33763449, 2020). "In mouse development studies, it was found that at embryonic stage (D7-9), HOXA1 expression precisely regulates the development of neural crest precursor cells, which are essential for tumor microenvironment remodeling." (PMID 33763449, 2020). "In TCGA-HNSC, HOXA1 expression in tumor tissues was significantly higher than adjacent tissues (p = 1.241e-10), the differential analysis of HOXA1 expression in 43 paired samples got the same result (p = 9.984e−09)." (PMID 33763449, 2020). "Among them, HOXA1 protein was detected in 45 cases (86.5%, + to ++) of tumor samples, while HOXA1 protein was detected in only ten sections (19.2%, + to ++) of adjacent pieces." (PMID 33763449, 2020). "Another candidate HOXB8, similarly to HOXA1, was a member of HOX family that was found to be significantly linked with tumor metastasis and shorter overall survival in many human cancers." (PMID 31787845, 2019). "The expressions of HOTAIRM1 and HOXA1 in GBM tissues and cells were determined by qRT-PCR, and the association between HOTAIRM1, HOXA1 transcription and tumor grade were analyzed." (PMID 30376874, 2018). "BC3_A2 cells were transduced with lentivirus encoding either HOXA1 or GFP, and infected tumor cells were mixed in different ratios." (PMID 29736411, 2018). "Hypoxia-induced miR-210 can regulate tumor cell susceptibility to cytolytic T-lymphocyte-mediated lysis by a mechanism involving its downstream targets PTPN1, HOXA1, and TP53I11." (PMID 29872497, 2018). "At the same time, Arg1 activity and ROS production were also reduced in MDSCs sorted from tumor tissues and spleen when HOXA1 was overexpressed." (PMID 29662483, 2018). "The results showed that the HOXA1 expression level was decreased in MDSCs from tumor tissues compared with those from adjacent tissue; similarly, the HOXA1 expression level was decreased in induced MDSCs compared with PBMCs." (PMID 29662483, 2018). "Among these genes, HOXA1 was more highly expressed in 8 out of 12 tumor tissues than in normal tissues." (PMID 26791264, 2016). "Coincidentally, our study revealed that HOXA1 knockdown in GC cells suppressed migration and invasion, which indicates the potential involvement of HOXA1 in tumor metastasis." (PMID 26791264, 2016). "The effects of HOXA1 on GC cell proliferation, migration, and invasion, as well as xenograft tumor formation and the cell cycle were investigated in our established stable HOXA1 knockdown GC cell lines." (PMID 26791264, 2016). "Knockdown of HOXA1 in GC cells not only inhibited cell proliferation, migration, and invasion in vitro but also suppressed xenograft tumor formation in vivo." (PMID 26791264, 2016). "We found a statistically significant correlation between HOXA1 and cyclin D1 expression (r = 0.476, P < 0.001), and HOXA1 and cyclin D1 expression were detected in the same location of one tumor specimen." (PMID 26791264, 2016). "We found that cyclin D1 expression was dramatically decreased in SGC-7901-shHOXA1 and BGC-823-shHOXA1 cells compared to the levels in the corresponding control cells, which indicates that HOXA1 influences tumor cell proliferation by regulating cyclin D1." (PMID 26791264, 2016). "Second, we studied the effects of HOXA1 on GC cell proliferation, migration, invasion, cell cycle progression, and xenograft tumor formation by knocking down the expression of HOXA1, and we found that the expression of cyclin D1 was also decreased." (PMID 26791264, 2016).
tumor (continued). "Forced expression of HOXA1 in normal human mammary epithelial cells is sufficient to initiate oncogenic transformation and tumor formation in vivo." (PMID 26417931, 2015). "Whereas all the control mice developed tumors, 75% of HOXA1 siRNA-nanoparticle-treated mice remained tumor-free at 21 weeks." (PMID 25927933, 2014). "They developed HOXA1-small interfering RNA nanoparticles and achieved effective therapeutic doses by delivering them intraductally through the nipple to the site of the tumor and at the same time circumvented the systemic immune response." (PMID 25927933, 2014). "We have observed that higher levels of HOXA1 were associated with larger tumor size at diagnosis, histopathologic differentiation of the tumor with high positivity for HOXA1 in undifferentiated tumors, and higher proliferative potential of the tumor." (PMID 22498108, 2012). "These tumor progression hallmarks were consistent with what was already described as induced by HOXA1 overexpression in other cell lines." (PMID 22498108, 2012). "Pre‐clinically, administration of nortriptyline (Nor) blocks the interaction of HOXA1 with PITX2, and suppresses the lysosomal exocytosis, tumor formation, and aggressive behavior, underscoring the functions of HOXA1/PITX2 axis in lysosomal exocytosis‐mediated SASP and cancer progression." (PMID 40995693, 2025). "Radiotherapy is a commonly used treatment method for cancer patients, and in this context, HOXA1 has been identified as an independent predictor of tumor progression, exhibiting a positive correlation with the expression of genes that enhance radiation resistance, including EGFR, CDK6, and CAV1." (PMID 38311789, 2024). "Furthermore, the data from OSCC-TCGA showed increased expression levels of HOXA1 in tumor samples compared to those in adjacent normal samples." (PMID 38473236, 2024). "Additionally, the role of the Wnt/β-catenin pathway, known to be significant in oncogenesis and tumor development, has been explored in relation to HOXA1." (PMID 38311789, 2024). "The abnormally high expression of the HOXA1/AKT/mTOR signaling pathway may be one of the key factors leading to tumor occurrence and development." (PMID 38628206, 2024). "Likewise, overexpression of HOXA1 has been demonstrated to promote tumor facilitative effects, including cell proliferation, metastasis, and invasion, in endometrial cancer (EC)." (PMID 38311789, 2024). "This cluster reduces tumor growth by inhibiting proteins involved in important cellular processes, including homeobox A1 (HOXA1), mammalian target of rapamycin (mTOR), insulin-like growth factor binding protein 1 (IGFBP1), and fibroblast growth factor receptor 3 (FGFR3)." (PMID 35327452, 2022). "Moreover, elevated HOXA1 expression promotes cell proliferation in gastric cancer and drives tumor growth and metastasis in melanoma." (PMID 36119466, 2022). "HOXA1 has diverse effects on tumor progression depending on the type of malignancy." (PMID 35693013, 2022). "Naturally expressed HOXA1 inhibitors have the ability to resist tumor progression and metastasis." (PMID 34180753, 2021). "The correlation analysis between DNA methylation level and HOXA1 expression showed that high HOXA1 expression with less promoter methylation in tumor samples (Pearson correlation coefficients ranging from −0.166 to −0.528 for promoter region probes) in the MEXPRESS database." (PMID 33763449, 2020). "Tumor immunity research is in full swing, and we are still full of unknowns on how the abnormal expression of HOXA1 affects immune function." (PMID 33763449, 2020). "Furthermore, the downstream axis involving KDM3A/HOXA1/MEIS3 was proposed to be essential for miR-202-3p to facilitate its functionality as a tumor suppressor." (PMID 33520978, 2020).